MYL3 (myosin light chain 3)
Description:
Regulatory light chain of myosin. Does not bind calcium.
Synonyms: MLC1SB; VLCl; MLC-lV/sb; CMH8; VLC1; MLC1V
Tractability: Small molecule: an approved drug acts on it; a structure with a bound ligand is known. PROTAC: ubiquitination databases record sites on it.
Gene: Protein-coding gene on chromosome 3 (46,835,109 to 46,885,911, reverse strand). Ensembl gene ENSG00000160808.
Subcellular location (Human Protein Atlas): Mitochondria; Nucleoli
Pathways (Reactome):
Muscle contraction: Striated Muscle Contraction
Gene Ontology:
Molecular function: actin monomer binding; cytoskeletal motor activity; myosin II heavy chain binding; structural constituent of muscle; calcium ion binding
Biological process: cardiac muscle contraction; regulation of striated muscle contraction; regulation of the force of heart contraction; ventricular cardiac muscle tissue morphogenesis; muscle contraction; skeletal muscle tissue development
Cellular component: A band; I band; cytosol; muscle myosin complex; myosin II complex; sarcomere; myosin complex
Genetic constraint (gnomAD): Loss-of-function variants: 11 observed, 22.45 expected, observed/expected ratio (o/e) 0.49, 90% interval 0.31 to 0.81. The upper end of that interval is the gene's LOEUF score, 0.81, which puts it in group 3 of 6, group 1 being the genes least tolerant of losing a copy. Missense variants: 206 observed, 265.31 expected, observed/expected ratio (o/e) 0.78, 90% interval 0.69 to 0.87. Synonymous variants: 88 observed, 96.89 expected, observed/expected ratio (o/e) 0.91, 90% interval 0.76 to 1.08.
Gene-disease validity (ClinGen):
ClinGen rates the evidence that MYL3 causes each of these diseases.
hypertrophic cardiomyopathy (autosomal dominant): Definitive. A condition in which the myocardium is hypertrophied without an obvious cause.
arrhythmogenic right ventricular cardiomyopathy (autosomal dominant): Limited.
dilated cardiomyopathy (autosomal dominant): Disputed. Cardiomyopathy which is characterized by dilation and contractile dysfunction of the left and right ventricles.
Homologues: Orthologues: macaque MYL3 (98% identical), mouse Myl3 (96% identical), chimpanzee MYL3 (95% identical), dog MYL3 (95% identical), pig MYL3 (95% identical), rat Myl3 (95% identical), guinea pig MYL3 (94% identical), rabbit MYL3 (89% identical), zebrafish myl4 (76% identical), zebrafish cmlc1 (70% identical), tropical clawed frog myl3 (69% identical), zebrafish zgc:163073 (60% identical), and 3 more. Paralogues in human: MYL4 (79% identical), MYL1 (70% identical), MYL6B (63% identical), MYL6 (56% identical).
Diseases named in the same sentence as MYL3 in open-access papers:
MYL3 is named in the same sentence as 54 diseases in open-access papers, as found by Europe PMC text mining. Sharing a sentence is not in itself a finding about the gene and the disease. The quoted sentences say what the papers report.
hypertrophic cardiomyopathy (17 papers, 2015 to 2025). "Research on the role of MYL3 in the diagnosis and treatment of hypertrophic cardiomyopathy has predominantly concentrated on genetic variants, with limited information available regarding the function of MYL3 itself in the regulation of cardiac hypertrophy." (PMID 40007621, 2025). "Pathogenic variants in this gene are associated with autosomal dominant MYL3-related cardiomyopathy, particularly familial hypertrophic cardiomyopathy." (PMID 38561731, 2024). "MYL3 is involved in muscle function and MYL3 gene mutations are associated with Hypertrophic cardiomyopathy." (PMID 37308827, 2023). "Mutations of MYH7 and MYL3 have been reported in various myopathies such as hypertrophic cardiomyopathy." (PMID 38173464, 2023). "Specifically, pediatric patients had more MYH7 and MYL3 variants in hypertrophic cardiomyopathy, and fewer TTN truncating variants in dilated cardiomyopathy." (PMID 37477868, 2023). "In addition, recent research identified a mutation in Myl3 that can cause hypertrophic cardiomyopathy in infants." (PMID 25695797, 2015). "In the cases of dilated cardiomyopathy, cardiac muscle contraction, and hypertrophic cardiomyopathy (B), seven downregulated proteins were enriched, including Myl2, Myl3, Myh7, Atp2a1, Tpm1, Tpm2, and Ttn." (PMID 39861068, 2024). "Meanwhile, in the hypertrophic cardiomyopathy pathway and adrenergic signaling in cardiomyocyte pathway, which are closely related to the occurrence of hypertrophic cardiomyopathy, myosin Light Chain 2 (Myl2) and myosin Light Chain 3 (Myl3) were the most significant proteins with lactylation." (PMID 40281739, 2025). "During the rest phase (CT30 and CT34), ECM-receptor interaction (e.g., Tnxb, Col4a1, and Col6a1) was the most enriched pathway among genes downregulated in WT KPC mice, while hypertrophic cardiomyopathy (e.g., Des, Tnnc1, and Myl3) was the most enriched pathway among upregulated genes." (PMID 40349340, 2025). "For example, TCAP (regulates sarcomere assembly and titin assembly; implicated in familial hypertrophic cardiomyopathy), MYL3 (myosin light chain 3; implicated in left ventricular hypertrophic cardiomyopathy and restrictive cardiomyopathy), LDB3, and DES were highly downregulated." (PMID 34338636, 2021). "KEGG pathway analysis on cardiac loop genes reveals enrichments for terms, such as dilated cardiomyopathy, vasopressin-regulated water reabsorption, and hypertrophic cardiomyopathy (the genes within these terms include: Adcy6, Aqp3, Creb3l4, Des, Itgb5, Itga9, Myl2, Myl3, and Stx4a)." (PMID 30697540, 2018). "The hypertrophic cardiomyopathy pathway contains upregulated genes like sarcoplasmic/endoplasmic reticulum calcium ATPase 1 (ATP2 A1), myosin light chain 3 (MYL3) and troponin C, skeletal muscle (TNNC2)." (PMID 40708816, 2025). "The results showed that genes (DES, MYH6, MYL2, MYL3, TPM1, TPM3, TPM4, and TTN) in MCODE 2 were significantly involved in dilated cardiomyopathy and hypertrophic cardiomyopathy (HCM)." (PMID 35645614, 2022). "Next, our KEGG analysis showed that transcripts up-regulated in the mutant cardiomyocytes were related to hypertrophic cardiomyopathy (ACTC1, MYL2, MYL3), Ca2+-dynamics regulatory pathway (ATP2B4, CACNA1C, CAMK2B, PLN), as well as cardiac-muscle contraction transcripts (ACTC1, MYH7, TNNI3, TNNT2)." (PMID 35784482, 2022).
cardiomyopathy (13 papers, 2011 to 2025). A disease of the heart muscle or myocardium proper. "Whole exome sequencing later revealed a homozygous mutation in the MYL3 (Myosin Light Chain 3) gene, associated with familial autosomal dominant MYL3-related cardiomyopathy." (PMID 38561731, 2024). "As a structural sarcomeric protein, MYL3 plays well-documented roles in muscle contraction and cardiomyopathies, but its limited topological influence in the interaction network reduced its composite ranking." (PMID 40725470, 2025). "Tg-E143K and Tg-D94A models of RCM and DCM, respectively, have been instrumental in confirming the perception that the mutations identified in MYL3 and MYL2 genes cause cardiomyopathy with typical features of human disease observed in these mouse models." (PMID 37511838, 2023). "Pathogenic variants in MYL2, MYL3 and MYL4 genes cause various isolated cardiomyopathies." (PMID 40488356, 2025). "Interestingly, protein and mRNA levels of MYH7, MYL3, and ACTC1, the major sarcomere genes whose variants can cause inherited cardiomyopathies such as HCM, and dilated cardiomyopathy were significantly increased in SCH cases." (PMID 37284852, 2023). "In April 2024, the ClinGen Cardiomyopathy Variant Curation Expert Panel (VCEP) adapted the ACMG/AMP criteria for eight of the sarcomeric genes (MYH7, MYBPC3, TNNI3, TNNT2, TPM1, ACTC1, MYL2, and MYL3), providing a refined framework for variant interpretation in these genes." (PMID 41357762, 2025). "However, 7 of them may be related to the processes associated with DCM since these candidate proteins were directly associated to other types of cardiomyopathies, such as HCM (e.g. MYL2 and MYL3)." (PMID 23940716, 2013). "Changes in the levels of myosin light chain 2 and myosin light chain 3 (MYL2 and MYL3) proteins upon isoproterenol treatment, observed in our study are consistent with the earlier observations of heart failure or cardiomyopathy." (PMID 23706090, 2013). "Although MYL2 and MYL3 have not been validated to be directly associated to DCM, their relationships with other cardiomyopathies have been mentioned in literature." (PMID 23940716, 2013).
dilated cardiomyopathy (11 papers, 2018 to 2025). "Hypertrophic and dilated cardiomyopathy causing mutations have been detected mostly in genes of sarcomere proteins such as Mybpc2, Myh7, Tnnt2, Tnnc1, Tnni3, Tpm1, Ttn, Actc1, Myl2, and Myl3." (PMID 38981849, 2024). "Additionally, heterozygous and homozygous variants in the MYL3 gene have been reported in patients with dilated cardiomyopathy, including loss-of-function variants." (PMID 38561731, 2024). "Necroptosis, neutrophil extracellular trap formation, cardiac muscle contraction, and dilated cardiomyopathy, among others, are some pathways affected by downregulated proteins such as Pgam5, Slc25a4, and H2ax as well as Myl2, Myl3, Atp2a1, and Tpm2." (PMID 41011134, 2025). "The impact of HCM mutations, as well as dilated cardiomyopathy (DCM) mutations can now be evaluated with this accurate high-resolution human β-cardiac IHM structure, including those affecting the MYL2 and MYL3 genes that code for the RLC and ELC proteins, respectively." (PMID 37258552, 2023).
cardiac hypertrophy (6 papers, 2018 to 2025). "Our study demonstrated that the down-regulation of MYL3 expression can effectively alleviate pathological cardiac hypertrophy, thereby offering new insights into the role of MYL3 in cardiac hypertrophy." (PMID 40007621, 2025). "The increased expression of MYL3 promoted autophagy and exacerbated cardiac hypertrophy through the modulation of PI3K/Akt/mTOR and ERK signaling pathways." (PMID 40007621, 2025). "In summary, circ-0001283 can bind directly to MYL3 and up-regulate its expression, thereby promoting autophagy to accelerate cardiac hypertrophy." (PMID 40007621, 2025). "Our current study demonstrated that the novel circRNA, circ-0001283, was up-regulated during cardiac hypertrophy and interacted with MYL3 protein in the cytoplasm." (PMID 40007621, 2025). "We evaluated the functional roles of circ-0001283 and MYL3 during pathological myocardial hypertrophy using an in vivo model." (PMID 40007621, 2025). "In conclusion, our study identified a novel circRNA, circ-0001283, which exacerbated cardiac hypertrophy in mice by targeting MYL3 and activating autophagy." (PMID 40007621, 2025). "It was found that circ-0001283 promoted the progression of cardiac hypertrophy by interacting with myosin light chain 3 (MYL3) to inhibit the protein ubiquitination and enhance its protein expression, not by the competitive endogenous RNA mechanism." (PMID 40007621, 2025). "A marked reduction in MYL2 and MYL3 protein and mRNA levels was also observed in the hearts of rats with isoproterenol-induced cardiac hypertrophy." (PMID 33498641, 2021). "In addition, MYL3 overexpression exacerbated cardiac hypertrophy in TAC mice with circ-0001283 knockdown." (PMID 40007621, 2025). "Moreover, the knockdown of either circ-0001283 or MYL3 alone in TAC mice resulted in reduced myocardial hypertrophy compared to the TAC + NC group." (PMID 40007621, 2025). "We hypothesized that circ-0001283 regulated cardiac hypertrophy via MYL3 or CSRP3." (PMID 40007621, 2025). "In this study, MYL3 was found to regulate the PI3K/Akt/mTOR and ERK signaling pathways, thereby promoting autophagy and aggravating myocardial hypertrophy." (PMID 40007621, 2025). "Studies have shown that MYL3 can interact with circRNA (circ-0001283) to regulate protein stability and activate PI3K/Akt/mTOR- and ERK-mediated autophagy signaling, thereby promoting cardiac hypertrophy progression." (PMID 40725470, 2025).
diabetic cardiomyopathy (2 papers, 2024 to 2025). Diabetic cardiomyopathy is a disorder of the heart muscle in people with diabetes. "Cluster 4 was enriched in genes of the ‘heart contraction’ (e.g., ACTC1, MYL3 and ACTA1) and ‘diabetic cardiomyopathy’ (e.g., TNNI3, MYH7 and GAS6)." (PMID 37766635, 2024). "Sciatic nerve proteomics showed a significant increase in LRP group myosin, TNN13, MYL7, MYL3, TNNC, MYBPC2, ACTN2, and KEGG enrichment analyses showed that these proteins were mainly enriched in pathways such as cardiac contraction, diabetic cardiomyopathy, and dilated heart disease." (PMID 40321612, 2025).
Hypertension (2 papers, 2024). The presence of chronic increased pressure in the systemic arterial system. "Similarly, proteins important for LV structure (MYL3), and mitochondrial function (COX5B), were up-regulated and down-regulated, respectively, in human hypertension." (PMID 38879891, 2024).
Obesity (2 papers, 2012 to 2024). Accumulation of substantial excess body fat. "The potential relation between a MYL3-based genetic predisposition, the hypertrophic phenotype and obesity in the proband should also strengthen the recommendation to the proband to lose weight." (PMID 22957257, 2012).
osteoarthritis (2 papers, 2023 to 2025). A noninflammatory degenerative joint disease occurring chiefly in older persons, characterized by degeneration of the articular cartilage, hypertrophy of bone at the margins and changes in the synovial membrane. "Myosin light chain 3 (MYL3) protein levels decline sharply in senescent chondrocytes of cartilages from model mice and osteoarthritis (OA) patients." (PMID 37794006, 2023). "Moreover, NOTCH inhibition in mice via myosin light-chain 3 maintenance has been shown to inhibit chondrocyte senescence and osteoarthritis." (PMID 39940287, 2025).
achromatopsia (1 paper, 2019). Achromatopsia (ACHM) is a rare autosomal recessive retinal disorder characterized by color blindness, nystagmus, photophobia, and severely reduced visual acuity due to the absence or impairment of cone function. "However, reanalysis helped to identify, in each parent, two heterozygous mutations in MYL3 and PDE6C, responsible for two different conditions: heart defect (OMIM #608751) and achromatopsia (OMIM #613093), respectively." (PMID 30665423, 2019).
anterior ischemic optic neuropathy (1 paper, 2023). Anterior ischemic optic neuropathy (AION) is an eye disease characterized by infarction of the optic disk leading to vision loss. "The “Myl3-CM” cardiomyocytes are enriched in transcripts associated with muscular diseases such as spinal muscular atrophy, myelofibrosis, and anterior ischemic optic neuropathy." (PMID 38110334, 2023).
cardiac arrest (1 paper, 2020). Cessation of breathing and/or cardiac function.
co-infection (1 paper, 2025). "In our co-infection study, MYL3 and TNNT2 downregulation indicates the suppression of genes essential for striated muscle contraction." (PMID 40943072, 2025). "The downregulation of MYL3, a sarcomeric protein, was specific to the Mc+ group, indicating more severe tissue damage after the subsequent co-infection with T. bryosalmonae." (PMID 40943072, 2025).
Ewing sarcoma (1 paper, 2023). A small round cell tumor that lacks morphologic, immunohistochemical, and electron microscopic evidence of neuroectodermal differentiation. "On the other hand, high expression of TTN and MYL3 genes can be described as a biomarker of a worse prognosis in Ewing’s sarcoma." (PMID 36982287, 2023).
Fabry disease (1 paper, 2025). Fabry disease (FD) is a progressive, inherited, multisystemic lysosomal storage disease characterized by specific neurological, cutaneous, renal, cardiovascular, cochleo-vestibular and cerebrovascular manifestations. "Of note, P.12 (female) carried homozygous MYL3 p.Ala57Asp together with a GLA variant of uncertain significance linked to Fabry disease; segregation data were unavailable to clarify pathogenicity." (PMID 41440877, 2025).
head and neck squamous cell carcinoma (1 paper, 2024). A squamous cell carcinoma that arises from any of the following anatomic sites: lip and oral cavity, nasal cavity, paranasal sinuses, pharynx, larynx, and salivary glands. "MYL1, MYL2, and MYL3 were shown to have a positive correlation between expression levels and the infiltration of CD4+T cells in head and neck squamous cell carcinoma (HNSCC)." (PMID 39768172, 2024).
Hernia (1 paper, 2021). "Furthermore, genes from the myosin family, the 1/3 myosin light chain skeletal muscle isoform (MYL1) and myosin light chain 3 (MYL3) have been described as candidate genes to the development of scrotal hernia in pigs, emphasizing the importance of muscle contraction in the development of hernias." (PMID 34773987, 2021).
Huntington disease (1 paper, 2023). Huntington disease (HD) is a rare neurodegenerative disorder of the central nervous system characterized by unwanted choreatic movements, behavioral and psychiatric disturbances and dementia. "A study in a mouse model of Huntington’s disease also reported elevated serum levels of Myl3 concomitant with skeletal muscle atrophy." (PMID 38110334, 2023).
Hypercholesterolemia (1 paper, 2022). An increased concentration of cholesterol in the blood. "Furthermore, hypercholesterolemia seemed to negatively affect the protein expression pattern of the ventricular isoform of myosin light chain (MYL3), as well as myosin heavy chain 6 (MYH6), which is preferably expressed in the ventricles of smaller mammals with rapid heart rates." (PMID 35806390, 2022).
lupus nephritis (1 paper, 2023). Glomerulonephritis in the context of systemic lupus erythematosus. "Two of the markers identified in our analyses, MYL3 and WIPF3, were GWAS hits for albuminuria, and one, ARMH4, was a hit for lupus nephritis." (PMID 36649229, 2023).
multiple sclerosis (1 paper, 2022). A progressive autoimmune disorder affecting the central nervous system resulting in demyelination. "Another interesting DEG, identified herein, also enriched in the “inhibition of remyelination in multiple sclerosis: regulation of cytoskeleton proteins” pathway, was the Myosin light chain 3 (MYL3)." (PMID 35804531, 2022).
muscle atrophy (1 paper, 2023). The loss of muscle tissue due to inactivity or disease. "Myl3 was described as DE in the ventricle and is associated with muscle atrophy and neuromuscular diseases." (PMID 38110334, 2023).
muscular dystrophy (1 paper, 2014). Muscular dystrophy (MD) refers to a group of more than 30 genetic diseases characterized by progressive weakness and degeneration of the skeletal muscles that control movement. "The strong and muscle-specific staining of CA3, MYL3, and TNNT3 in healthy tissue indicates that detection of increased levels of these targets in blood samples of muscular dystrophy patients originates from the muscle, as these targets are not expressed in other tissues." (PMID 24920607, 2014). "Comparison of the two muscular dystrophy phenotypes, DMD and BMD, in the UNEW cohort revealed again CA3 as an important contributor for the separation of these two patient groups and MDH2 and MYL3 for separation of the BMD patients and female carriers in both blood preparation types." (PMID 24920607, 2014).
myopia (1 paper, 2024). "Because the retina is a neural tissue, the expression of numerous genes linked to cardiac muscle (MYBPC3, ACTC1, MYL3, MYH7, MYH7B) or to skeletal muscle (MYL1, SMYD1, TNNI2, MYH1B, ACTA1, TNNT3) presents a conundrum for explaining a mechanism for myopia progression." (PMID 39028695, 2024).
Skeletal myopathy (1 paper, 2023). "Biallelic PTVs in MYBPC3, TNNI3, MYL2 and MYL3 are associated with severe, early-onset CM phenotypes, which can include additional features such as atrial and ventricular septal defects and skeletal myopathy." (PMID 38666070, 2023).